RBP7 (retinol binding protein 7)
Diseases named in the same sentence as RBP7 in open-access papers (continued):
Sharing a sentence is not in itself a finding about the gene and the disease.
tumor (continued). "Univariate and multivariate analyses showed that NDRG1 and RBP7 were independent prognostic factors for OS, and RBP7 might act as a tumor suppressor gene in hormone receptor-positive breast cancer." (PMID 38553715, 2024). "As an immune-related gene, the multifarious role of RBP7 in tumor is promising." (PMID 38553715, 2024). "The results showed that patients with high RBP7 expression had lower tumor T-stage." (PMID 38553715, 2024). "Overexpression of RBP7 significantly decreased xenograft tumor volume, while downregulation of RBP7 could reverse the effect." (PMID 38553715, 2024). "The results indicated that patients with high RBP7 expression had lower tumor T stage." (PMID 38553715, 2024). "We defined the RBP7 as a tumor immune microenvironment-related gene for CRC to 5-FU resistance." (PMID 35784334, 2022). "In this study, we identified immune-related genes to 5-FU resistance in the tumor microenvironment and found that RBP7 has the potential to predict chemotherapy resistance and poor prognosis of CRC patients, which will hopefully provide a biomarker for 5-FU resistance and prognosis for CRC patients." (PMID 35784334, 2022). "RBP7 may function as a tumor microenvironment regulator to induce 5-FU resistance, thereby affecting the prognosis of CRC patients." (PMID 35784334, 2022). "Importantly, ectopic expression of RBP7 increased the number of migrated and invaded tumor cells, and these effects were comparable in both cell lines." (PMID 31598160, 2019). "Moreover, proportional hazards regression analysis demonstrated that high RBP7 expression was an independent predictor of poor tumor specific survival in this case collection (HR = 2.54; P = 0.009)." (PMID 31598160, 2019). "In addition, in this data set RBP7 levels increased with T-category and thus with the depth of bowel wall infiltration, suggesting a link of RBP7 and tumor invasion." (PMID 31598160, 2019). "In addition, the expression pattern of RBP7 in the the tumor microenvironment suggested that RBP7 may mediate 5-FU resistance by regulating the tumor microenvironment." (PMID 35784334, 2022). "RBP7, another important member of the RBP family, is gaining attention for its potential role in tumor biology." (PMID 41301068, 2025). "For instance, up-regulation of ADIPOQ, AGTR1, AHNAK, ENDRA, RBP7 and SLIT2 was correlated with larger tumour size and more advanced tumour stage." (PMID 33184436, 2020). "This study highlighted RBP7 as a novel prognostic biomarker and is another piece of evidence that the SREBP1-dependent lipogenesis is a promising target to disrupt tumorigenesis and tumor progression." (PMID 40427160, 2025).
RBP7 also shares sentences with these, for which no sentence is quoted: bladder cancer (2 papers); Bardet-Biedl syndrome (1); CNS cancer (1); esophageal cancer (1); head and neck cancer (1); infection (1); Joubert syndrome (1); leukemia (1); liver cancer (1); lung adenocarcinoma (1); lymphoma (1); nasopharyngeal carcinoma (1); osteoarthritis (1); uterine corpus endometrial carcinoma (1); viral infection (1).